TNFRSF11B (TNF receptor superfamily member 11b)
Diseases named in the same sentence as TNFRSF11B in open-access papers (continued):
Sharing a sentence is not in itself a finding about the gene and the disease.
colon carcinoma (continued). "Using a single-cell database, we also demonstrated that TNFRSF11B affected the terminal phase of cell differentiation, metastasis, angiogenesis and the inflammatory response in colon cancer." (PMID 34938284, 2021). "To determine which genes and pathways are responsible for TNFRSF11B expression in colon cancer, we performed transcriptome-wide RNA-sequencing analysis of colon cancer tissues and paired colon epithelium." (PMID 34938284, 2021). "We analyzed the potential role of TNFRSF11B in the differentiation of colon cancer via a GSE81861 array." (PMID 34938284, 2021). "Moreover, we assessed the differential role and related pathways of TNFRSF11B in the progression of colon cancer via gene set enrichment analysis (GSEA) and pseudotime analysis." (PMID 34938284, 2021). "Finally, we shed light on the suppressive role of TNFRSF11B in the tumor infiltration of activated memory CD4+ T cells in colon cancer." (PMID 34938284, 2021). "An immunohistochemistry (IHC) dataset (n = 86), 290 single colorectal cancer cells (GSE81861), and 31 paired colon cancer transcriptional datasets were further applied to validate the function of TNFRSF11B, which was confirmed via fluorescence-activated cell sorting (FACS) analysis." (PMID 34938284, 2021). "TNFRSF11B acts as a prognostic factor for colon cancer patients and could affect the colon cancer immune response." (PMID 34938284, 2021). "We hypothesized that TNFRSF11B may regulate YWHAZ transcriptional activity to affect tumorigenesis in colon cancer." (PMID 34938284, 2021). "TNFRSF11B may correlate with IL17A in the regulation of the colon cancer immune response." (PMID 34938284, 2021). "All these findings indicated that TNFRSF11B may promote lymph node metastasis in colon cancer." (PMID 34938284, 2021). "Furthermore, the accumulation of soluble TNFRSF11B in the peripheral blood of colon cancer patients could result in a poorer survival rate, especially in patients with TNM stage III disease." (PMID 34938284, 2021). "We found that the expression levels of some genes enriched in IL-11+ fibroblasts, including Wnt5a, Mmp13, Timp1, Il1rl1, Cxcl5, Saa3, Inhiba, Ascl4, and Tnfrsf11b, were elevated in mouse AOM/DSS-induced colon tumor tissues." (PMID 33863879, 2021). "A risk score system consisting of eight immune-related genes (IRGs) (FGFR2, ZC3HAV1L, TNFRSF11B, CD79A, IGHV3-11, IGHV3-21, IGKV2D-30, and IGKV6D-21) was constructed to predict the prognosis of colon cancer patients." (PMID 34938284, 2021). "A risk scoring system consisting of eight IRGs (FGFR2, ZC3HAV1L, TNFRSF11B, CD79A, IGHV3-11, IGHV3-21, IGKV2D-30, and IGKV6D-21) was constructed to evaluate the prognosis of colon cancer patients based on multivariate Cox analysis." (PMID 34938284, 2021).
glioma (6 papers, 2019 to 2024). A benign or malignant brain and spinal cord tumor that arises from glial cells (astrocytes, oligodendrocytes, ependymal cells). "Univariate and multivariate regression analyses further confirmed the Riskscore, TNFRSF11b, and TNFRSF12a as independent risk factors in The Cancer Genome Atlas and Chinese Glioma Genome Atlas datasets." (PMID 35592520, 2022). "Since the previous studies have explored the role of the signature genes METTL7B, SSTR2, OXTR, CDKN2C, and H19 in glioma, while TNFRSF11B has been poorly studied, we examined the functional impact of TNFRSF11B on LGG cell behavior." (PMID 37713112, 2024). "Moreover, the increase in TNFRSF11B expression has been demonstrated to enhance the movement and infiltration of glioma cells, while also providing protection against chemotherapy medications in laboratory settings." (PMID 38560169, 2024). "In addition, TNFRSF11B might be involved in the malignant progression of gliomas and was one of the signature genes that predicted patient prognosis." (PMID 36437961, 2022). "From this perspective, TNFRSF11B may inactivate the RANK-RANKL pathway and further protect the patients with gliomas." (PMID 35592520, 2022).
melanoma (4 papers, 2021 to 2025). A malignant, usually aggressive tumor composed of atypical, neoplastic melanocytes. "Similar results have been reported in another non-osteogenic environment with a higher presence of TNFα leading to the upregulation of TNFRSF11B in melanoma cells, which in that instance promoted tumor cell survival." (PMID 40665262, 2025). "Two genes, TNFRSF11B and TNFRSF14 that were correlated with the invasion capacity of melanoma cells in our experiments, are part of this prediction system." (PMID 35269787, 2022).
Osteopenia (4 papers, 2016 to 2025). Osteopenia is a term to define bone density that is not normal but also not as low as osteoporosis. "Tnfrsf11b-deficient (Opg–/–) mice exhibited severe osteopenia with enhanced bone resorption and formation." (PMID 32792620, 2020).
Paget disease (4 papers, 2020 to 2023). A malignant neoplasm composed of large cells with large nuclei, prominent nucleoli, and abundant pale cytoplasm (Paget cells). "SNPs located near TNFSF11, TNFRSF11A, and TNFRSF11B have been reported to be closely associated with Paget's disease, osteoporotic fractures, cardiovascular diseases, ankylosing spondylitis, and breast, and esophageal cancers." (PMID 34660648, 2021). "Paget’s disease involves a number of genetic factors including the TNFRSF11A and TNFRSF11B genes which encode for RANK and osteoprotegerin (OPG), respectively." (PMID 34068971, 2021). "Partial deletion of TNFRSF11B resulted in a dramatic increase in RANKL-RANK interactions, which eventually led to juvenile Paget’s disease." (PMID 32117996, 2020).
rheumatoid arthritis (4 papers, 2015 to 2021). A chronic, systemic autoimmune disorder characterized by inflammation in the synovial membranes and articular surfaces. "Additionally, the TNFRSF11B rs2073618 was significantly associated with Type 2 Diabetes, rheumatoid arthritis, and volumetric bone mineral density." (PMID 34660648, 2021).
bronchiectasis (2 papers, 2020 to 2021). Segmental, irreversible dilation of the bronchial tree resulting in the accumulation of secretions which leads to obstruction. "A recent study identified different inflammation profiles when comparing gingival tissues of bronchiectasis patients having chronic periodontitis, with 7 genes significantly altered in bronchiectasis patients (LTA, LTB, TNFSF4, TNFSF11, TNFSF13, TNFSF13B, and TNFRSF11B)." (PMID 34765263, 2021).
colorectal cancer (2 papers, 2021 to 2023). A primary or metastatic malignant neoplasm that affects the colon or rectum. "We also performed FACS analysis to show that TNFRSF11B decreased the infiltration of central memory CD4+ T cells and effector memory CD4+ T cells in the colorectal cancer microenvironment (all p <0.001)." (PMID 34938284, 2021). "TNFRSF11B is regulated via the Wnt/β-catenin pathway, contributes to resistance against apoptosis induced by TRAIL, and is found at elevated levels in the serum of patients with advanced colorectal cancers." (PMID 38049731, 2023).
COVID-19 (2 papers, 2022 to 2023). A disease caused by infection with severe acute respiratory syndrome coronavirus 2. "We also identified increased Tnfrsf11b, which is a discriminator of severe COVID-19 neurological symptoms in patients." (PMID 38259435, 2023). "Furthermore, plasma IL-8, IL-6, TNFRSF11B, and CSF EZR levels were allied to severe COVID-19 using the ordinal backward and best linear model, whereas plasma 4E-BP1 and CSF levels of PD-L1, BMP-4, CLEC10A and ROBO2 withstanded using one model only." (PMID 36351919, 2022).
Hypertension (2 papers, 2013 to 2017). The presence of chronic increased pressure in the systemic arterial system. "Among the DEGs that were down-regulated in the hypertension plus hypercholesterolemia group were FOXN1, TNFRSF11B, and GAPDHS." (PMID 23874591, 2013).
inflammatory bowel disease (2 papers, 2016 to 2021). A spectrum of small and large bowel inflammatory diseases of unknown etiology. "Previous research on patients with inflammatory bowel disease (IBD) has identified several genes (IL13RA2, TNFRSF11B, STC1, IL-6, and IL-11) that constitute potential biomarkers that can identify patients with limited response to IFX, which is consistent with our study." (PMID 34650991, 2021).
ischemic stroke (2 papers, 2013 to 2019). A stroke disorder caused by obstruction of blood flow to the brain, due to thrombotic (local blood clot formation) or embolic (due to a blood clot or other material traveling from another site) event. "Polymorphism in TNFRSF11B was identified with development of ischemic stroke, but this gene may be important for progression of CAD." (PMID 31881747, 2019). "Gene polymorphism of TNFRSF11B is a risk factor for ischemic stroke." (PMID 23874591, 2013).
liver cancer (2 papers, 2022 to 2023). An epithelial or non-epithelial malignant neoplasm that arises from the liver. "Studies have shown that in highly aggressive liver cancer cells, the expression of TNFRSF11B is often lower than that of low aggressive liver cancer cells." (PMID 35397536, 2022).
lymph node metastasis (2 papers, 2021 to 2025). "Overexpression of TNFRSF11B obviously correlated with late-stage lymph node metastasis and worse survival outcomes (p = 0.010, p = 0.014, and p = 0.0061, respectively)." (PMID 34938284, 2021). "Only TNFRSF11B was closely correlated with late-stage lymph node metastasis and worse survival outcomes (p = 0.010, p = 0.014, and p = 0.0061)." (PMID 34938284, 2021).
Obesity (2 papers, 2017 to 2020). Accumulation of substantial excess body fat. "Furthermore, a specific study on obesity-mediated inflammatory microenvironment in 2011 validated the specific contribution of TNFRSF11B as a bone disease-associated gene on the pathogenesis of obesity." (PMID 29258237, 2017). "In 2016, TNFRSF11B was reported to participate in obesity-induced metabolic bone disease of women given its detailed relationship with bone disease." (PMID 29258237, 2017). "Using the system biology approach, we mined a set of genes influenced by obesity to uncover five genes (FABP4, CFD, GHR, TNFRSF11B, and LTF) as previously unrecognized contributors to the development of TC." (PMID 33240576, 2020). "Five out of the 358 obesity-specific genes, FABP4, CFD, GHR, TNFRSF11B, and LTF, presented significantly decreased expression in TC patients (LFC<−1.44; and p-value < 1e−7)." (PMID 33240576, 2020). "Thereby, decreased levels of GHP, TNFRSF11B, and LTF in obesity could facilitate the pathologic development of TC." (PMID 33240576, 2020).
Type 2 Diabetes (2 papers, 2013 to 2021). "In humans, plasma TNFRSF11B levels are elevated in patients with cardiovascular risk factors such as type 2 diabetes and abdominal obesity." (PMID 24040759, 2013).
amyotrophic lateral sclerosis (1 paper, 2022). Amyotrophic lateral sclerosis (ALS) is a neurodegenerative disease characterized by progressive muscular paralysis reflecting degeneration of motor neurons in the primary motor cortex, corticospinal tracts, brainstem and spinal cord. "Additionally, some cases of PDB-like syndromes have been attributed to mutations in VCP, TNFRSF11A, TNFRSF11B, HNRNPA2B1, HNRNPA1, ZNF687 and PFN1, most of which are known to involved in the amyotrophic lateral sclerosis (ALS) and nuclear factor kappa B (NF-kB) signaling pathways." (PMID 35355568, 2022).
aortic aneurysm (1 paper, 2024). A ruptured aneurysm located in the wall of the proximal portion of the descending aorta proceeding from the arch of the aorta. "Finally, immunostaining on human aortic aneurysms showed increased TNFRSF11B and IGFBP2 proteins in TAAs relative to AAAs, validating the bioinformatic analysis performed on mouse tissues." (PMID 39590192, 2024).
astrocytoma (1 paper, 2022). "There, genes with a higher expression in glioblastoma compared to astrocytoma were VEGFA, 4EBP1, CCL2, PLAU (uPA), CXCL8 (IL8), CXCL10 (IP10), CASP8, HGF, LIF, CD40, CDCp1, TNFRSF11B (OPG), CD274 (PD-L1), IL6, CXCL1, CCL20 (MIP3α), CCL8 (MCP2), CD244, MMP1, TNFRSF9, CXCL6, MMP10, FGF5)." (PMID 35301393, 2022).
Blindness (1 paper, 2015). Blindness is the condition of lacking visual perception defined as a profound reduction in visual perception. "Ocular localization of the proteins that showed significantly higher expression in the vitreous than in blood (CCL2, IGFBP2, MMP10, HGF, TNFRSF11B) was investigated in histological specimens of eyes from patients with painful blindness due to secondary glaucoma after CRVO." (PMID 25978399, 2015).
bone tumor (1 paper, 2023). "We hypothesize that excess TNFRSF11B copies may contribute to bone tumor development by increasing protein expression, leading to dysregulation of the balance between bone formation and resorption." (PMID 37445641, 2023).
carotid atherosclerosis (1 paper, 2015). A thickening and loss of elasticity of the walls of carotid arteries that occur with formation of atherosclerotic plaques. "Osteoprotegerin gene (TNFRSF11B) polymorphisms were also recently shown to be potential markers for carotid calcified plaques in patients with carotid atherosclerosis." (PMID 26122709, 2015).
cervical cancer (1 paper, 2023). A primary or metastatic malignant neoplasm involving the cervix. "TNFRSF11B, also termed osteoprotegerin, was demonstrated to involve in the progression of gastric cancer, melanomas and colon cancer but little was known about its function in cervical cancer." (PMID 36816023, 2023).
coronary atherosclerosis (1 paper, 2015). Atherosclerosis of the coronary vasculature. "The major finding of this study is that a polymorphism of the TNFRSF11B gene, which encodes osteoprotegerin, is associated with the presence of coronary atherosclerosis in patients with RA." (PMID 25679449, 2015).
dementia (1 paper, 2026). Loss of intellectual abilities interfering with an individual's social and occupational functions. "TNFRSF11B, a protein linked to vascular damage, was associated with both incident dementia and reduced hippocampal volume." (PMID 41555457, 2026). "Mediation analyses indicated that TNFRSF11B, APOE and C7 may partially mediate associations between modifiable risk factors and dementia." (PMID 41555457, 2026).
diabetes (1 paper, 2023). "Similarly, TNFα addition in bECs, but not in mEC, upregulated the expression of TNFRSF11B, whose increased serum levels have been found in patients with inflammatory pathologies such as diabetes or atherosclerosis." (PMID 36721025, 2023).
diabetic kidney disease (1 paper, 2010). Progressive kidney disorder caused by vascular damage to the glomerular capillaries, in patients with diabetes mellitus. "(a) TNFRSF11B and TNFSF10 are members of the tumour necrosis factor super family, which is known to be associated with diabetic kidney disease, lupus nephritis, and ANCA-associated glomerulonephritis." (PMID 21070623, 2010).
E. coli) infection (1 paper, 2021). "Our findings showed that only pathogenic E. coli infection was altered in tumor tissues and tumors highly expressing TNFRSF11B via a specific GSEA approach." (PMID 34938284, 2021). "The expression of six genes (KRT18, ARPC5L, ACTG1, ARPC2, EZR, and YWHAZ) related to pathogenic E. coli infection was simultaneously increased with TNFRSF11B overexpression via gene set enrichment analysis (GSEA)." (PMID 34938284, 2021). "Pathogenic Escherichia coli (E. coli) infection, drug metabolism, other enzymes and Vibrio cholerae infection were the other three pathways activated by the increased expression of TNFRSF11B." (PMID 34938284, 2021). "Consistently, only the pathogenic E. coli infection pathway was significantly elevated with the increasing level of TNFRSF11B among tumors Normalized Enrichment Score (NES) = 1.814, p = 0.004) and in the comparison of tumors with paired colon epithelium (NES = 1.523, p = 0.027)." (PMID 34938284, 2021). "TNFRSF11B may affect the transcriptional activity of YWHAZ to regulate pathogenic E. coli infection, which was further validated in the TCGA-COAD database, in which increased TNFRSF11B expression correlated with increased TWHAZ expression (cor = 0.185, p <0.001)." (PMID 34938284, 2021). "TNFRSF11B correlates with colonic mucosal immunity and is increased in the presence of E. coli infection resulting in diarrhea, and the potentiation of Peyer’s patch M cell self-renewal ability to ameliorate the inflammatory response can facilitate Salmonella infection." (PMID 34938284, 2021).
gastric tumor (1 paper, 2020). "Inhibition of TNFRSF11B expression may provide a novel treatment for gastric tumor patients with overexpression of TNFRSF11B." (PMID 32398963, 2020).
gastric ulcer (1 paper, 2023). An ulcerated lesion in the mucosal surface of the stomach. "In the RNA-seq analysis of gastric ulcer tissue induced by indomethacin, the DEGs between the IND group and the HMLS group revealed a notable decrease in the expression of tnfrsf11b, an inflammation-related gene." (PMID 38139257, 2023).
hemorrhagic stroke (1 paper, 2015). A stroke caused by a bleed on the brain. "Single nucleotide polymorphisms (SNPs) rs1035798 in RAGE gene, rs2073617 and rs2073618 in TNFRSF11B, and rs3732410 in Golgb1 will be investigated on whether there is an association with hemorrhagic stroke (HS) in Chinese population." (PMID 26664786, 2015).
Hepatic steatosis (1 paper, 2016). Steatosis is a term used to denote lipid accumulation within hepatocytes. "The top three genes (apoe, a2m and tnfrsf11b) were found to be regulated by SENP3 in hepatic steatosis in vitro." (PMID 27853276, 2016).
HIV encephalitis (1 paper, 2010). "TNFRSF11B is one out of 50 genes identified as high expression in frontal cortex of HIV encephalitis (HIVE) vs HIVE-control patients." (PMID 20920282, 2010). "TNFRSF11B computational development network construction and analysis of frontal cortex of HIV encephalitis (HIVE) is very useful to identify novel markers and potential targets for prognosis and therapy." (PMID 20920282, 2010). "TNFRSF11B computational development network construction and analysis of the frontal cortex of HIV encephalitis (HIVE) is very useful to identify novel markers and potential targets for prognosis and therapy." (PMID 20920282, 2010).
Hyperglycemia (1 paper, 2020). An increased concentration of glucose in the blood. "We observed significant downregulation of Mafa, Ins1, and Ins2 mRNAs, and significant upregulation of Aldob, Slc5a10, Wnt5b, Hk1, and Tnfrsf11b mRNAs, suggesting that the molecular defect results directly from the loss of Cnot3, rather than to hyperglycemia." (PMID 32859966, 2020).
hyperphosphatasia (1 paper, 2022). "The mutation in the TNFRSF11B gene can cause deficiency of osteoprotegerin leading to hereditary hyperphosphatasia. mRNAs that could help the production of osteoprotegerin would be a great strategy to treat such a hereditary disorder." (PMID 35424872, 2022).
myocardial infarction (1 paper, 2024). Gross necrosis of the myocardium, as a result of interruption of the blood supply to the area, as in coronary thrombosis. "TNFRSF11B plays a significant role in several cardiovascular diseases, including coronary artery syndromes and myocardial infarction." (PMID 38333413, 2024).
oral squamous cell carcinoma (1 paper, 2025). "TNFRSF11B, a member of the tumor necrosis factor receptor superfamily, is highly expressed in several tumor types, including oral squamous cell carcinoma, and is associated with increased tumor cell survival, angiogenesis, and metastatic potential." (PMID 41303490, 2025).
osteoarthrosis (1 paper, 2011). "TNFRSF11B and BAX have been reported to be associated with osteoarthrosis by previous studies." (PMID 21829570, 2011).
osteosarcoma (1 paper, 2024). A usually aggressive malignant bone-forming mesenchymal neoplasm, predominantly affecting adolescents and young adults. "Therefore, we speculate that STC2 and TNFRSF11B may play a more critical role in the progression of osteosarcoma." (PMID 39119088, 2024).